TMC2 (transmembrane channel like 2)
Description:
Pore-forming subunit of the mechanotransducer (MET) non-selective cation channel complex located at the tips of stereocilia of cochlear hair cells and that mediates sensory transduction in the auditory system. The MET complex is composed of two dimeric pore-forming ion-conducting transmembrane TMC (TMC1 or TMC2) subunits, and aided by several auxiliary proteins including LHFPL5, TMIE, CIB2/3 and TOMT, and the tip-link PCDH15. MET channel is activated by tension in the tip-link extending from the side wall of one stereocilium to the tip of the adjacent shorter stereocilium, where the channel is located (By similarity). TMC2 MET channel is highly permeable to calcium and likely transports monovalent cations. Also involved in vestibular hair cell transduction current of the mammalian inner ear (By similarity).
Synonyms: C20orf145; dJ686C3.3
Tractability: Antibody: UniProt places it where antibodies can reach, with medium confidence; UniProt predicts a signal peptide or a membrane-spanning region; its Gene Ontology location is reachable by antibodies, with medium confidence.
Gene: Protein-coding gene on chromosome 20 (2,536,573 to 2,643,580, forward strand). Ensembl gene ENSG00000149488.
Subcellular location: Cell membrane
Pathways (Reactome):
Sensory Perception: Sensory processing of sound by inner hair cells of the cochlea; Sensory processing of sound by outer hair cells of the cochlea
Gene Ontology:
Molecular function: calcium channel activity; mechanosensitive monoatomic ion channel activity; voltage-gated calcium channel activity
Biological process: detection of mechanical stimulus involved in sensory perception of sound; vestibular reflex; calcium ion transmembrane transport; monoatomic ion transmembrane transport
Cellular component: cuticular plate; plasma membrane; stereocilium; membrane; stereocilium tip
Genetic constraint (gnomAD): Loss-of-function variants: 83 observed, 86.55 expected, observed/expected ratio (o/e) 0.96, 90% interval 0.8 to 1.15. The upper end of that interval is the gene's LOEUF score, 1.15, which puts it in group 5 of 6, group 1 being the genes least tolerant of losing a copy. Missense variants: 875 observed, 954.86 expected, observed/expected ratio (o/e) 0.92, 90% interval 0.87 to 0.97. Synonymous variants: 334 observed, 366.5 expected, observed/expected ratio (o/e) 0.91, 90% interval 0.83 to 1.
Homologues: Orthologues: chimpanzee TMC2 (99% identical), macaque TMC2 (96% identical), pig TMC2 (88% identical), dog TMC2 (88% identical), rabbit TMC2 (87% identical), mouse Tmc2 (82% identical), rat Tmc2 (81% identical), guinea pig TMC2 (81% identical), zebrafish tmc2a (57% identical), zebrafish tmc2b (56% identical), Drosophila melanogaster Tmc (35% identical). Paralogues in human: TMC1 (47% identical), TMC3 (36% identical), TMC7 (18% identical), TMC6 (17% identical), TMC8 (16% identical), TMC5 (16% identical), TMC4 (16% identical).
Diseases named in the same sentence as TMC2 in open-access papers:
TMC2 is named in the same sentence as 7 diseases in open-access papers, as found by Europe PMC text mining. Sharing a sentence is not in itself a finding about the gene and the disease. The quoted sentences say what the papers report.
deafness (7 papers, 2015 to 2025). An inherited or acquired condition characterized by the complete loss of the ability to hear from one or both ears. "Mutations in LOXHD1, OTOF, PCDH15, TBL1X, and TMC2 have been associated with hereditary disorders of balance, deafness or hearing loss in humans (NCBI gene db and GeneCards)." (PMID 32770228, 2020). "Mutations in the TMC1 and TMC2 cause deafness in humans and mice." (PMID 33193678, 2020). "In this study, we sought to test the hypothesis that persistent Tmc2 expression could substitute for loss of Tmc1 expression in mature cochlear HCs in a mouse model of Tmc1-deficient deafness." (PMID 30108230, 2018). "Furthermore, we report that calcium and integrin-binding protein 2 binds to the components of the hair cell mechanotransduction complex, TMC1 and TMC2, and these interactions are disrupted by deafness-causing Cib2 mutations." (PMID 28663585, 2017). "It has been found that TMC1 knockout mice exhibit complete deafness but retain vestibular function, partly because TMC2 continues to be expressed in vestibular hair cells." (PMID 41049429, 2025). "TMC1 and TMC2 were initially identified in human deafness patients, and studies have shown that they also play key roles in mice and zebrafish." (PMID 41049429, 2025). "In conclusion, transgenic expression of Tmc2 in mature cochlear HCs partially restored cochlear HC and auditory function in a Tmc1-deficient mouse model of DFNB7/B11 deafness." (PMID 30108230, 2018). "Of particular interest is expression of TMC2, a putative component of the hair cell transduction channel, and myosin XV, a known deafness gene expressed in hair cell stereocilia." (PMID 26560106, 2015). "TMC1 and TMC2 play a crucial role in the mechanoelectrical transduction of hair cells and may also mediate hair cell damage and apoptosis, leading to deafness, by affecting intracellular Ca2+ homeostasis." (PMID 41049429, 2025). "Studies have shown that the role of TMC2 deficiency in deafness should not be overlooked." (PMID 41049429, 2025).
hearing loss (2 papers, 2020 to 2025). "Our data identify the mechanistic basis for this membrane-related hearing loss and indicate that TMC1 and TMC2 can function as both MS channel and lipid scramblases." (PMID 40631239, 2025).
sensorineural hearing loss (1 paper, 2022). "TMC1 was identified by positional cloning of a gene underlying nonsyndromic sensorineural hearing loss and was shown to be one of two isoforms, along with TMC2, that is required for mechanoelectrical-transduction in hair cells of the mouse inner ear." (PMID 36191207, 2022).
Sepsis (1 paper, 2025). Sepsis is defined as life-threatening organ dysfunction caused by a dysregulated host response to infection. "Genes such as TMC2, TNFSF10, and CTNNA1 were the most significant predictors of sepsis severity." (PMID 40362669, 2025).
cancer (1 paper, 2021). A tumor composed of atypical neoplastic, often pleomorphic cells that invade other tissues. "The data from the FANTOM5, HPA, and databases showed concordant results that the TMC1 and TMC2 were almost not expressed in all analyzed tissues and cancer types." (PMID 34899684, 2021).
cardiovascular disease (1 paper, 2020). "A study in the Han Chinese population reported that TMC2 was among the top genes associated with BP response to the cold pressor test (CPT), which is associated with an increased risk of cardiovascular disease." (PMID 32315356, 2020).
TMC2 also shares sentences with these, for which no sentence is quoted: tumor (1 paper).